HMGA2 (high mobility group AT-hook 2)
Diseases named in the same sentence as HMGA2 in open-access papers (continued):
Sharing a sentence is not in itself a finding about the gene and the disease.
hepatocellular carcinoma (continued). "HMGA2 staining data were unrelated to parameters of cancer aggressiveness in hepatocellular carcinoma, squamous cell carcinomas of different sites of origin, muscle-invasive urothelial carcinoma, serous high-grade carcinoma of the ovary, as well as in gastric and pancreatic adenocarcinoma." (PMID 40518465, 2025). "Likewise, the circRNA Circ-CCND1 exacerbates hepatocellular carcinoma by modulating the miR-497-5p/HMGA2 axis." (PMID 39591457, 2024). "Overexpression of HMGA2 promoted cell migration in hepatoma cell lines." (PMID 39664573, 2024). "Similarly, the lncRNA HULC (highly upregulated in liver cancer) is overexpressed in hepatocellular carcinoma and promotes liver cancer growth through increasing the expression of the HMGA2 oncogene via sequestration of the microRNA-186." (PMID 37232821, 2023). "It has been detected to have higher expression in hepatocellular carcinoma (HCC), associated with worse clinical outcomes, and functions as an oncogene by interacting with the transcription factor HMGA2 to activate the Wnt/β-catenin signaling pathway in hepatocellular carcinoma." (PMID 36292141, 2022). "Interestingly, HMGA2-sh-3p20 elevated HMGA2 expression in hepatoma cells by means of preventing TTP binding to the HMGA mRNA." (PMID 30380668, 2018). "Then, we focused on the investigation that the function of HMGA2-sh in hepatoma cells." (PMID 28522832, 2017). "Therefore, we conclude that HMGA2-sh-3p20 contributes to the growth of hepatoma cells in vitro and in vivo." (PMID 28522832, 2017). "Thus, we conclude that fragment HMGA2-sh-3p20 from HMGA2 mRNA 3′UTR promotes the growth of hepatoma cells by upregulating HMGA2." (PMID 28522832, 2017). "Thus, we conclude that HMGA2-sh-3p20 antagonizes TTP-mediated the degradation of HMGA2 mRNA by targeting itself HMGA2 mRNA, resulting in upregulation of HMGA2 in hepatoma cells." (PMID 28522832, 2017). "Here, we explore the hypothesis that HMGA2 may enhance the growth of hepatoma cells through a fragment based on the secondary structure of HMGA2 mRNA 3′-untranslated region (3′UTR)." (PMID 28522832, 2017). "Thus, we conclude that the fragment HMGA2-sh-3p20 from HMGA2 mRNA 3′UTR promotes the growth of hepatoma cells by upregulating HMGA2." (PMID 28522832, 2017). "The expression of let-7g is extremely low in hepatocellular carcinoma (HCC) and re-expression of let-7g miRNA in HCC cells inhibited tumor cell proliferation and migration via inhibition of K-Ras/HMGA2/Snail axis." (PMID 34572067, 2021). "Additionally, miR663a’s downregulation fostered cell proliferation by JunD overexpression in small-cell lung carcinoma, and HMGA2 in hepatocellular carcinoma, while Transforming Growth Factor-1 (TGF-β1) overexpression was linked with invasion in the tumour type." (PMID 32102337, 2020). "Therefore, we conclude that HMGA2-sh-3p20 contributes to the growth of hepatoma cells." (PMID 28522832, 2017). "In hepatocellular carcinoma, an oncogenic EGF-EGFR-PI3K/Akt pathway was shown to increase p300 HAT-mediated H3K9 acetylation of the HMGA2 promoter, resulting in higher HMGA2 gene expression and a poor prognosis." (PMID 36835656, 2023). "In hepatocellular carcinoma, lncRNA LSINCT5 acted as a competing endogenous RNA and sponged miR-4516 in regulated HMGA2 expression." (PMID 32549762, 2020). "In hepatocellular carcinoma, the upregulation of TET1 could drive cell growth through aberrant enhancer hydroxymethylation of HMGA2." (PMID 36195596, 2022). "However, the mechanism by which HMGA2 promotes the growth of hepatocellular carcinoma (HCC) remains unclear." (PMID 28522832, 2017).
hepatocellular carcinoma (continued). "The inhibitor of HMGA2-sh-3p20 failed to downregulate the expression of HMGA2 at the levels of mRNA and protein, implying that the levels of HMGA2-sh-3p20 are lower in hepatoma cells." (PMID 28522832, 2017). "It is not known, however, whether HMGA2 regulates EMT in human hepatocellular carcinoma (HCC) cell lines, and the mechanism(s) have not been fully elucidated." (PMID 23599793, 2013). "However, the expression of HMGA2 has not been reported in clinical hepatocellular carcinoma (HCC)." (PMID 28522832, 2017). "Then, we speculated that hairpin and non-hairpin HMGA2 might co-exist in hepatoma cells." (PMID 28522832, 2017). "It is not known whether HMGA2 regulates EMT in human hepatocellular carcinoma (HCC) cell lines; furthermore, the mechanism(s) have not been fully elucidated." (PMID 23599793, 2013).
Uterine leiomyoma (36 papers, 2010 to 2025). The presence of a leiomyoma of the uterus. "While FH and COL4A5/6 mutations have been characterized, the majority of uterine leiomyoma (80–90%) harbor MED12 or HMGA2 alterations." (PMID 35203298, 2022). "We also analysed SNPs on driver genes such as MED12, FH, and HMGA2 which harbor somatic mutations in uterine leiomyoma." (PMID 31988393, 2020). "Previous investigations clearly point to a number of different genetic subtypes of uterine leiomyomas with those affected by mutations of MED12 representing by far the most frequent sub-entity followed by that showing rearrangements of HMGA2." (PMID 29963223, 2018). "Recurrent rearrangements affecting the chromosomal band 12q14 are known to cause an overexpression of HMGA2 in uterine leiomyomas." (PMID 24516594, 2014). "In this study we created 15-state chromatin annotations for myometrium, and MED12, HMGA2, and FH uterine leiomyomas." (PMID 40341524, 2025). "Most usual uterine leiomyomas (40–75%) are characterized by MED12 mutation, followed by 10–25% with HMGA2 overexpression." (PMID 37466765, 2024). "It has been shown that three main uterine leiomyoma molecular subtypes exist, including tumors with MED12 mutation, molecular aberrations leading to HMGA2 overexpression, and biallelic loss of FH." (PMID 37466765, 2024). "Three main uterine leiomyoma molecular subtypes include tumors with MED12 mutation, molecular aberrations leading to HMGA2 overexpression, and biallelic loss of FH." (PMID 37466765, 2024). "Genetic alterations associated with uterine leiomyoma are heterogeneous and they include mutations of mediator complex subunit 12 (MED12), overexpression of high mobility group AT-hook 2 (HMGA2), and inactivation of the fumarate hydratase (FH) gene." (PMID 38642139, 2024). "Uterine leiomyomas are benign smooth muscle tumors that can be classified into at least three molecular subtypes, reflecting mutations in either MED12, HMGA2, or FH." (PMID 36068196, 2022). "HMGA2 plays a key role in the onset of uterine fibroids and resides in the chromosomal rearrangements affecting the 12q14-15 region that targets the HMGA2 gene." (PMID 35885889, 2022). "While alterations of MED12 and HMGA2 are most common in uterine leiomyomas, a range of other genetic pathways have been described." (PMID 31027501, 2019). "Alterations of mediator complex subunit 12 (MED12) and high mobility group AT-hook 2 (HMGA2) are the most common genetic aberrations in uterine leiomyomas." (PMID 31027501, 2019). "In uterine leiomyomas, HMGA2 fusion transcripts were reported with various sequences including COX6C (8q22.2), ALDH2 (12q24.12), CCNB1IP1 (14q11.2), RAD51B (14q24.1), and RTVL-H 3_ LTR (21q21.2)." (PMID 28591699, 2017). "Recently, uterine leiomyomas with HMGA2 aberrations were shown to display highly significant up-regulation of PLAG1." (PMID 28591699, 2017). "A strong correlation of PLAG1 and HMGA2 expression was also detected in a number of thyroid carcinomas and uterine leiomyomas and cell culture experiments led to the conclusion that HMGA2 is an upstream activator of PLAG1." (PMID 25923053, 2015). "A correlation between chromosomal rearrangements affecting the HMGA2 locus and the HMGA2 protein expression has been shown in uterine leiomyomas." (PMID 24516594, 2014). "Several recurrent genetic aberrations, such as trisomy of chromosome 12, deletions in 7q, and mutation affecting the mediator complex subunit 12 (MED12) or the high mobility group AT-hook 2 (HMGA2) gene were reported in uterine leiomyomas." (PMID 22570742, 2012). "Furthermore, COX6C participates in oncogenic rearrangements, including gene fusions with HMGA2 in uterine leiomyoma and translocations in retroperitoneal lipomas and thyroid carcinomas." (PMID 41157129, 2025).
Uterine leiomyoma (continued). "The HMGA2 locus is affected in mesenchymal tumors, including adipogenic tumors and uterine leiomyoma, suggesting that the locus may be a fragile target for dynamic chromosomal rearrangement, especially in case #52." (PMID 32825119, 2020). "In addition, uterine leiomyoma harbors genetic alteration of some driver genes including MED12 mutations, biallelic inactivation of FH, and HMGA2 rearrangements." (PMID 31988393, 2020). "On the other hand, mutations of MED12 have not been detected in uterine leiomyomas with 12q14∼15 rearrangements resulting in overexpression of HMGA2." (PMID 28591699, 2017). "Mutations of mediator subcomplex 12 (MED12) and of high mobility group protein AT-hook 2 (HMGA2) are driver mutations in uterine leiomyomas (UL) that have not been observed to coexist in one tumor and even rarely coexist in different UL tumors of one patient." (PMID 26468330, 2015). "In uterine leiomyomas, the inverse physiological relationship between let-7 and HMGA2 also persists such that large leiomyomata were observed to express low levels of let-7 and high levels of HMGA2, while small leiomyomata expressed high levels of let-7 and low levels of HMGA2." (PMID 32365712, 2020). "MED12 is reported to be the most frequently altered gene in uterine leiomyomas, and changes in either MED12 or HMGA2 are present in 80%-90% of uterine leiomyomas." (PMID 35305104, 2022). "The results presented herein point to HMGA2 as an upstream regulator of PLAG1 and are additionally confirmed by the correlation between the expressions of both genes in uterine leiomyomas." (PMID 24516594, 2014). "Yet, there are multiple benign tumors like chondroid hamartomas of the lung, uterine leiomyomas or adenomas of the salivary glands that display HMGA2 rearrangements, but do not accumulate fat." (PMID 33235355, 2021). "Until recently, MED12 and HMGA2 were thought to be mutually exclusive genetic events since no uterine leiomyomas had been found to harbor both alterations." (PMID 31027501, 2019). "Mutations of MED12 have, on the other hand, not been detected in uterine leiomyomas with 12q14~15 rearrangements resulting in overexpression of HMGA2." (PMID 25621995, 2015). "However, the potential mechanisms by which HMGA2 could affect tamoxifen response were not addressed, although a close relation of HMGA2 and ERα was identified in studies on cervical cancer and uterine leiomyoma." (PMID 36980520, 2023). "While it has been suggested that alteration of HMGA2 is considered to be the initial step leading to significant upregulation of PLAG1, the role of RAD51B should not be overlooked, as it is also important in uterine leiomyoma development." (PMID 37466765, 2024).
colon carcinoma (35 papers, 2010 to 2025). "It was discovered that when colon cancer cells overexpressed HMGA2, DIC might cause apoptosis and prevent the cells from migration." (PMID 39803273, 2025). "It was additionally suggested that in breast and colon cancers, HMGA2 induced the metastasis as well as invasion of cancer cells through TGFβ signaling." (PMID 38671227, 2024). "In particular, for Panc1 and Panc89 cell lines, comparable expression was detected in cytosolic and nuclear fractions, while HMGA2 was more present in the nuclear fraction of BxPC3 cells and in the colon cancer cell line HCT116." (PMID 34302528, 2021). "Similar to our data, a previous report indicated that Slug expression is critical for the HMGA2-induced promotion of EMT in colon cancer." (PMID 31109142, 2019). "Higher expression of HMGA2 has been seen in breast, ovarian and colon cancer and pancreatic adenocarcinoma." (PMID 30763339, 2019). "After quantification of HMGA2 protein in different cell lines the colon cancer derived cell line HCT116 was chosen for further ChIP experiments because of its 3.4-fold higher HMGA2 protein level." (PMID 21533145, 2011). "Out of 2000 analyzed genes, DDB2, but not XPC nor HMGA2, significantly associated with hazard ratio of 2.1 in a group of oxaliplatin-treated colon cancer patients." (PMID 38058548, 2023). "Besides, HMGA2 is commonly upregulated in many types of cancer, and was correlated with poor prognosis and lower survival rates in colon cancer." (PMID 34707995, 2021). "It was found that DIC could trigger apoptosis and inhibit the migration of colon cancer cells that over-expressed HMGA2." (PMID 34707995, 2021). "The sensitizing effect of low‐to‐moderate HMGA2 expression to irinotecan treatment was also demonstrated in patient‐derived xenograft models of human colon cancer, and we mechanistically ascribed these outcomes to a potentiating drug effect in ternary scDNA‐TOP1‐HMGA2 complexes." (PMID 31271486, 2019). "We found that KLK6 overexpression in colon cancer cells, regardless of its enzymatic activity, induces the expression of transcription associated protein HMGA2, which has been identified as a driver of the CRC progression and metastasis." (PMID 31692974, 2019). "While prior studies show that HMGA2 is overexpressed in colon cancer and Hmga2 drives tumorigenesis in mouse models with Let-7 deficiency, we focus on HMGA1 since transcripts are approximately 100-fold higher than HMGA2 in colon cancer datasets (TCGA) and in many other human tumors." (PMID 39895630, 2025). "It offered a fresh perspective on the molecular role of HMGA‐2 and proposed a potential therapeutic use of DIC to stop the spread of colon cancer cells that overexpress HMGA‐2." (PMID 39803273, 2025). "HMGA2 also directly induces the target gene SLUG to promote EMT, migration, and proliferation of colon cancer cells." (PMID 36945110, 2023). "In our dataset, we encouraged the histochemical cytoplasmic HMGA2 staining by analyzing cytoplasmic and nuclear fractions of three PDAC cell lines as well as a colon cancer cell line." (PMID 34302528, 2021). "More importantly, the AAACA site of circNSUN2 directly binds the 3′UTR of HMGA2 with AU-rich elements; HMGA2 has been reported to induce EMT and contribute to colon cancer progression." (PMID 33536039, 2021).
colon carcinoma (continued). "The colon cancer cell lines HT-29, LS 174T, and SW620 express high levels of high-mobility group AT-hook 2 (HMGA2) transcriptional regulating factor, compared to the normal colon epithelial cell line CCD18Co." (PMID 31200510, 2019). "Thus, targeted inhibition of HMGA2 may be crucial for the treatment of colon cancer." (PMID 27095441, 2016). "Additionally, HMGA2 induces invasion and cell migration and regulates EMT markers in the colon cancer cell lines HT-29 and LS 174T." (PMID 31200510, 2019). "Moreover, the miR-204/HMGA2 axis modulated the resistance of tumor cells to 5-Fu in HCT-116 and SW480 colon cancer cells via activation of the PI3K/AKT pathway." (PMID 27095441, 2016). "HCT-116 colon cancer cells have constitutively active Wnt/β-catenin signalling but do not express as high levels of HMGA2 as in TNBC cell lines." (PMID 23307470, 2013).
glioblastoma (32 papers, 2012 to 2026). The most malignant astrocytic tumor (WHO grade IV). "LncRNA LINC00152 promoted the progression of glioblastoma by targeting miR-107 and regulating the expression of HMGA2." (PMID 34856955, 2021). "HMGA2 is a transcriptional modulator that is known to promote stemness, invasion and tumorigenicity in glioblastoma (GBM)." (PMID 34419065, 2021). "Interestingly, the “guide strand” of miR-142-3p is negatively modulated by interleukin-6 in glioblastoma multiforme (GBM), the most aggressive and stem cell-rich primary brain tumour, causing the upregulation of HMGA2 protein expression." (PMID 31979076, 2020). "Re-expression of HMGA2 enhances mesenchymal transition of glioblastoma and self-renewal of glioblastoma SCs." (PMID 33291403, 2020). "Igf2bp2 is a target of HMGA2 in different cell types; it is an mRNA binding protein also involved in stem cell maintenance in glioblastoma, a neural tumor in which HMGA2 is reactivated." (PMID 31963852, 2020). "The authors concluded that HMGA2 should be considered as a stem-like factor of glioblastoma cells, guaranteeing clonogenicity, invasion, and malignant properties." (PMID 29853899, 2018). "In brain tumors, we recently reported that LIN28A promotes invasion and tumorigenesis in glioblastoma in part through upregulation of HMGA2." (PMID 25638158, 2015). "Furthermore, HMGA2 expression increases more than 9-fold in CD133-positive population of glioblastoma multiforme (GBM) neurosphere cells compared to CD133-negative cells." (PMID 33668453, 2021). "HMGA2 is also involved in glioblastoma stem cell maintenance." (PMID 31963852, 2020). "Similarly, phenformin has been shown to target the let-7/HMGA2 axis and has been proposed to be effective in combination with temozolomide against glioblastoma." (PMID 31979076, 2020). "In addition, upregulation of the HMGA2/IL-6 axis was shown to be highly correlated with poor outcomes in glioblastoma patients." (PMID 32842685, 2020). "According to P value obtained from log-rank test, we found that the HMGA2 expression was significantly higher than corresponding normal tissues in 17 types of cancers except glioblastoma multiforme, kidney chromophobe, kidney renal clear cell carcinoma and prostate adenocarcinoma." (PMID 29997523, 2018). "In glioblastoma (GBM), M2-TAMs inhibit miR-340-5p by upregulating transforming growth factor β-1 and promoting basement membrane HMGA-2 expression." (PMID 36479040, 2022). "The expression of HMGA2 and IGF2BP2 increased in seven established glioblastoma cell lines after anti-Let-7 treatment." (PMID 27102443, 2016). "miR-142-3p is a target of Interleukin 6 (IL6) in glioblastoma and it has been proposed that miR-142-3p blocks the expression of IL6, Hmga2 and Sox2 thereby suppressing the stem like properties of glioblastomas." (PMID 26327117, 2015). "In addition, H19 regulates High Mobility Group AT-Hook 2 (HMGA2) expression and microRNAs, both of which enhance the mesenchymal transition of glioblastoma and self-renewal of GSCs." (PMID 39015773, 2024). "In addition, our results showed that the Let-7 target genes (HMGA2, IGF2BP2, and LIN28B) were significantly upregulated in glioblastoma patient-derived cells (GBM04T) after anti-Let-7 treatment." (PMID 27102443, 2016).